KEAP1 (kelch like ECH associated protein 1)
Diseases named in the same sentence as KEAP1 in open-access papers (continued):
Sharing a sentence is not in itself a finding about the gene and the disease.
Hyperkeratosis (22 papers, 2008 to 2025). Hyperkeratosis is a histopathological term defining a thickened stratum corneum and may be present in many different skin conditions, with many possible overlaps. "Keap1-knockout mice die before weaning due to obstruction of the esophagus and forestomach caused by hyperkeratosis of the squamous cell epithelium." (PMID 35204110, 2022). "The constant mechanical load in the squamous epithelium and the disrupted NRF2-KEAP1 complex likely lead to excessive hyperkeratosis in Keap1-deficient mice." (PMID 32823937, 2020). "Most interestingly, however, the skin, esophagus, and forestomach of Keap1-deficient mice show cornified layer and hyperkeratosis phenotypes." (PMID 18629308, 2008). "Surprisingly, these Keap1-deficient mice also show a thicker stratum corneum epidermis, abnormal keratinization, and cornification in the esophagus and forestomach (hyperkeratosis)." (PMID 18629308, 2008). "Thus, lethal hyperkeratosis in Keap1-deficient mice or Nrf2-mediated epidermal barrier repair in LKO mice are important examples of such adaptive responses in the epidermis." (PMID 32823937, 2020). "Indeed, mice with constitutively active Nrf2, due to loss of Keap1, die at young age due to hyperkeratosis." (PMID 26885667, 2016). "It is unknown why hyperactive Nrf2 in Keap1−/− mice caused hyperkeratosis of the esophageal epithelium at P7." (PMID 22567161, 2012). "Hence, based on these results and on the findings from studies of Keap1 knockout mice, iAs may both cause hyperkeratosis and induce detoxification enzymes via the modification of NRF2." (PMID 18629308, 2008). "In vivo, studies have shown that keratinocytes undergo proliferation by NRF2 activation through a fibroblast‐senescent phenotype that results in excessive growth‐factor release or even hyperkeratosis in KEAP1 knock‐out rodents." (PMID 40353553, 2025). "It is known that complete deletion of Keap1 in Nrf2ꜛ mice leads to death from malnutrition due to hyperkeratosis of the esophagus shortly after birth." (PMID 36979025, 2023). "This retardation is caused by malnutrition and dehydration due to obstruction of the esophagus and forestomach secondary to hyperkeratosis, a phenotype also observed in systemic Keap1‐knockout mice." (PMID 37306101, 2023). "This represented almost a phenocopy of Keap1‐deficient mice, which exhibit hyperactivation of NRF2 and show hyperkeratosis in the esophagus and forestomach." (PMID 37306101, 2023). "Keap1–/– mice are rescued from juvenile lethality, and hyperkeratosis is largely avoided in Nrf2 heterozygous compound mutant mice (Keap1–/–::Nrf2+/–), indicating that massive Nrf2 expression is required to provoke severe hyperkeratosis of the esophagus." (PMID 36230622, 2022). "We found that while the wild-type Keap1 transgene (Tg-Keap1WT) is able to rescue esophageal hyperkeratosis in Keap1–/– mice, Keap1 point mutant transgenes (Tg-Keap1 mutant), including C273&288A, G364C and G430C, cannot rescue hyperkeratosis and lethality." (PMID 36230622, 2022). "In fact, severe hyperkeratosis in the esophageal epithelium is observed as the most characteristic phenotype in Keap1 systemic knockout (Keap1–/–) mice." (PMID 36230622, 2022). "As Keap1floxA/– mice show milder hyperkeratosis than Keap1–/– mice, Keap1floxA/– mice can survive with the remaining Keap1 mRNA expression, which is approximately 10% of the level of wild-type mice." (PMID 36230622, 2022). "Consistent with the phenotype in Keap1–/– mice, the hyperkeratosis of the esophagus and forestomach in Keap1floxA/– mice is also diminished by the transgenic expression of wild-type KEAP1 (Tg-Keap1WT)." (PMID 36230622, 2022). "On the other hand, systemic Keap1 knockout (Keap1-KO) mice starve to death during the weaning period because of impaired feeding due to hyperkeratosis of the upper gastrointestinal tract, suggesting that Nrf2 induces the expression of genes encoding keratin." (PMID 32331329, 2020).
Hyperkeratosis (continued). "The KEAP1-mediated repression of NRF2 activity is critical for our bodies, as indicated by the targeted deletion of KEAP1 in mice resulting in lethal hyperkeratosis in the upper digestive tract." (PMID 33375248, 2020). "For example, unopposed activity of the Nrf2-mediated oxidative stress response by KEAP1 ablation leads to epidermal hyperkeratosis and increased expression of keratinocyte differentiation markers in mice." (PMID 32076005, 2020). "In good agreement with the improvement of hyperkeratosis, the juvenile lethality of Keap1−/−::Nrf2Flox/Flox mice was rescued." (PMID 28233855, 2017). "Consistent with the Nqo1 and Gclc expression, the hyperkeratosis of the oesophagus and forestomach observed in Keap1−/−::Nrf2Flox/Flox mice was rescued in NEKO mice." (PMID 28233855, 2017). "Some evidence supports this notion, such as its known roles: first, Keap1-knockout mice, in which Nrf2 is constitutively active, developed hyperkeratosis in the esophagus and forestomach." (PMID 28282941, 2017). "Whereas Nrf2−/− mice grow normally under normal conditions, Keap1−/− mice died postnatally because of hyperkeratosis in the esophagus and forestomach." (PMID 27198574, 2016). "Keap1−/− mice died within three weeks after birth, probably due to malnutrition as a result of hyperkeratosis in the esophagus and forestomach." (PMID 22567161, 2012). "Microarray and immunostaining data also suggested that esophageal hyperkeratosis in the Keap1−/− mice was due to activation of Pparβ/δ and the PI3K/Akt pathway." (PMID 22567161, 2012). "Similar to the esophagus, the skin was also hyperkeratic in Keap1−/− mice, suggesting similar mechanisms of hyperkeratosis in the skin and the esophagus." (PMID 22567161, 2012). "It has been reported that disruption of Keap1 in mice leads to hyperkeratosis in esophagus, forestomach, and skin, most likely because of constitutive activation of NRF2 and aberrant expression of some ARE-dependent cytokeratins." (PMID 22476201, 2012). "This is explained by the fact that, in knock-in mice expressing p62S351E, in which autophagy is intact but p62 strongly binds to KEAP1, hyperkeratosis is observed in the stratified squamous epithelium of the esophagus and stomach, but the mice showed only mild liver enlargement and damage." (PMID 40437287, 2025). "Meanwhile, Keap1 mRNA expression in Keap1floxA/floxA mice completely disappeared in the presence of K5-Cre recombinase, so keratinocyte-specific Keap1 knockout (Keap1floxA/floxA::K5Cre) mice died before weaning due to severe hyperkeratosis of the esophagus, similar to Keap1–/– mice." (PMID 36230622, 2022). "Systemic Keap1-knockout mice in which Nrf2 activity is constitutively activated macroscopically exhibit scaling skin, and histological examinations reveal the presence of severe hyperkeratosis in the skin, esophagus and forestomach." (PMID 35204110, 2022). "Intriguingly, Nrf2−/− mice develop normally, except that these mice are more sensitive to chemical carcinogens, whereas Keap1−/− mice die shortly after birth because of hyperkeratosis of the forestomach and esophagus as a result of hyperactivation of the NRF2 pathway." (PMID 32053600, 2020). "However, Keap1-null mice are juvenile lethal due to hyperkeratosis in the upper digestive tract, which leads to the obstruction of the oesophagus and death by starvation." (PMID 28233855, 2017). "Indeed, genetic deletion of Nrf2 in keratinocytes rescues Keap1-KO mice from lethal hyperkeratosis." (PMID 32331329, 2020). "Intriguingly, Keap1–/–::Tg-Keap1WT::Tg-Keap1mutant mice show hyperkeratosis and juvenile lethality, whereas Keap1 heterozygous knockout mice (Keap1+/–) have no obvious changes in the esophagus." (PMID 36230622, 2022). "Keap1−/− mice at postnatal day (P) 7 showed growth retardation; however, there were no histological abnormalities other than hyperkeratosis in the upper digestive tract, which is related to the juvenile lethality." (PMID 33707458, 2021).
Hyperkeratosis (continued). "In this study, we generated a new mouse model, NEKO, which has high Nrf2 activity due to Keap1 deletion but without juvenile lethality and hyperkeratosis of the upper digestive tract." (PMID 28233855, 2017).
injury (22 papers, 2014 to 2026). Damage inflicted on the body as the direct or indirect result of an external force, with or without disruption of structural continuity. "The PPIs between Kelch-like ECH-associated protein 1 (Keap1) and Nrf2 play a critical role in acute lung injury." (PMID 36479199, 2022). "Treated groups with L-carnitine showed upregulation of Nrf2/Keap1/NQO1 expression which proposed that Nrf2/Keap1/NQO1 activation is implicated in the therapeutic effect of L-carnitine against acute lung injury." (PMID 34169163, 2021). "Also, it is noted that the Kelch-like ECH-associated protein 1 (Keap1)/erythroid 2-related factor 2 (Nrf2)/heme oxygenase-1 (HO-1) is a crucial pathway axis in defense against paracetamol-induced liver injury." (PMID 40569949, 2025). "Another study indicated that silymarin administration alleviated thioacetamide-induced acute liver injury by activating the Nrf2/Keap1 pathway." (PMID 38539857, 2024). "In this study, UA treatment led to Keap1-Nrf2/HO-1 pathways activation in LPS-induced acute lung injury ferroptosis, while inhibiting the Keap1-Nrf2/HO-1 pathways significantly abolished trehalose’s function in suppressing ferroptosis." (PMID 36969874, 2023). "Our data indicated that Keap1/Nrf2 signaling activation was required for MFAEs function in acute/chronic liver injury." (PMID 37032323, 2023). "Augmentation of constitutive Nrf2 activity by small molecules that disrupt Keap1:Nrf2 interactions was effective in conferring protection against oxidant-induced acute lung injury in adult mice." (PMID 33149211, 2020). "We found that H2S promotes S-sulfhydrated Keap1 in SM-treated lung cells, demonstrating that Keap1 S-sulfhydration plays a significant role of in the protective effects of H2S against SM-induced lung injuries." (PMID 28842592, 2017). "It is suggested that Icariin, the effective component of total flavones from stems and leaves of Epimedium optimized by extraction technology, may play a protective role in CTX-induced mouse kidney injury through the Keap1-Nrf2 pathway." (PMID 38202790, 2023). "We hypothesize that Ks extracts may exert protective effects against APAP-induced acute liver injury by modulating the SPHK1/S1P/S1PR2/S1PR4 pathway and the Nrf2/Keap1 pathway, thereby mediating oxidative stress and inflammatory responses." (PMID 40811614, 2025).
Sepsis (22 papers, 2013 to 2025). Sepsis is defined as life-threatening organ dysfunction caused by a dysregulated host response to infection. "Our study demonstrated the protective effects of cognitive decline from microglia mitochondrial fragmentation by Mdivi‐1 after sepsis through alleviating microglia polarization and neuroinflammation probably via NF‐κB and Nrf2/Keap1/HO‐1." (PMID 39791542, 2025). "Collectively, our data suggest that BBR inhibits pyroptosis and inflammation in sepsis‐induced acute gastric injury through the activation of the Keap1/Nrf2 signaling pathway." (PMID 39484787, 2024). "Our research reveals that BBR interacts with Keap1 to activate the Keap1/Nrf2 signaling pathway in gastric epithelial cells, thereby suppressing pyroptosis and inflammation in sepsis‐induced acute gastric injury." (PMID 39484787, 2024). "As an important mediator of Nrf2 degradation, KEAP1 has been found to promote the sepsis-involved cellular as well as organ damage." (PMID 37056939, 2023). "In studies on sepsis, miRNA miR-125b-5p has been found to play an active role in inflammation, directly targeting Keap1 and reducing cell-death-induced inflammation through the Keap1/Nrf2/GPX4 pathway, thereby improving acute lung injury caused by sepsis." (PMID 37686375, 2023). "Mice with a Keap1 deletion in the myeloid lineage confer significantly reduced sepsis progression and improved survival." (PMID 33348637, 2020). "We therefore performed a comprehensive approach to study Nrf2/Keap1 signaling in MDSCs in steady state and sepsis and identified Nrf2 as a key metabolic regulator of these immunosuppressive cells." (PMID 30034396, 2018). "In this section, we will explore signaling pathways involved in the inflammatory response during sepsis, with a particular focus on the MAPK, hypoxia-inducible factor 1α (HIF-1α), and nuclear factor-erythroid 2-related factor 2/Kelch-like ECH-associated protein 1 (Nrf2/Keap1) pathways." (PMID 41041277, 2025). "Vincamine exhibited hepato-protective potential during CLP-induced sepsis via the cross-connection of antioxidant, anti-inflammatory, and anti-apoptotic activities by modulating TNFα/IL-6/IL-1β/Nrf-2/Keap-1 and regulating bax/bcl2/cleaved caspase 3 signaling pathways." (PMID 39174578, 2024). "A study showed that EVs from adipose-derived stem cells specifically deliver miR-125b-5p to alleviate inflammation-induced pulmonary microvascular endothelial cell ferroptosis in sepsis-induced ALI by modulating Keap1/Nrf2/GPX4 expression, thereby improving acute lung injury." (PMID 39809198, 2024). "Furthermore, miR-125b-5p present in EVs from ADSCs can alleviate inflammation-induced ferroptosis in pulmonary microvascular endothelial cells (PMVECs) during sepsis-induced ALI by regulating the expression of Keap1/Nrf2/GPX4." (PMID 38343439, 2023). "Similarly, sepsis-initiated acute liver injury can be prevented or ameliorated by pharmacological Nrf2 activation or by its genetic stabilization by Keap1 disruption." (PMID 33348637, 2020). "Moreover, the Nrf2/Keap1 system acts as a critical modulator in the process of sepsis." (PMID 39484787, 2024). "Inhibition of Keap1 expression with Keap1 siRNA significantly promoted the accumulation of NRF2 and increased the expression level of GPX 4, and finally alleviated lung tissue damage in sepsis." (PMID 39670103, 2024). "Our results showed that sepsis does not alter cardiac KEAP1 expression, but induces instead its phosphorylation at T85 through upregulation of STK3." (PMID 37056939, 2023).
depression (21 papers, 2016 to 2025). "The Nrf2/KEAP1 pathway is an important tool to control redox homeostasis and improve functional outcomes in depression associated with MS." (PMID 37508537, 2023). "Recent studies have shown that the Nrf2/KEAP1 signaling pathway has been implicated as a key factor in MS-associated depression." (PMID 37508537, 2023). "Decreased levels of endogenous anti-inflammatory proteins Nrf2 and Keap1 in the CA3 hippocampus of mice have been implicated in the pathophysiology of depression after social defeat stress." (PMID 34565419, 2021). "Low levels of Keap1-Nrf2 in mPFC and hippocampus are reportedly associated with the development of depression-like phenotypes, including anhedonia, in rodents." (PMID 30135655, 2018). "Accumulating evidence suggests that the transcription factor Kelch-like erythroid cell-derived protein with CNC homology (ECH)-associated protein 1 (Keap1)-Nuclear factor (erythroid-derived 2)-like 2 (Nrf2) system plays a key role in inflammation which is involved in depression." (PMID 30386243, 2018). "The Keap1/Nrf2/HO-1 pathway plays a core regulatory role in LPS-induced inflammatory responses and depression." (PMID 40427467, 2025). "LPS-induced inflammation can lead to oxidative stress and neuronal damage, while the Keap1/Nrf2/HO-1 pathway integrates antioxidant and anti-inflammatory effects, serving as a common molecular hub linking inflammation and depression." (PMID 40427467, 2025). "The regulatory role of 5-HMF as an Nrf2 inducer acting on the Keap1–Nrf2 complex in depression will be confirmed in this study." (PMID 41300522, 2025). "Our results suggested that PF improved the LPS-induced depression-like behavior in mouse models of depression, inhibiting Keap1-mediated Nrf2 degradation and activation of the NLRP3 inflammasome." (PMID 40427467, 2025). "In our study, we found that PF alleviates LPS-induced neuroinflammation and depression through the Keap1/Nrf2/HO-1 signaling pathway." (PMID 40427467, 2025). "The results of the rescue experiments provide preliminary evidence that cuproptosis inhibition and the alleviation of TBI‐related depression through circSpna2 were accomplished by binding Keap1 and then regulating Nrf2 expression." (PMID 39581695, 2024). "Specifically, we proposed that circSpna2 can play an important role in cellular responses to oxidative stress by modulating the Keap1‐Nrf2 signalling pathway and has significant effects on neuroprotection and depression." (PMID 39581695, 2024). "This is the first evidence that circSpna2 can ameliorate post‐TBI depression by attenuating cuproptosis through the circSpna2/Keap1/Nrf2/Atp7b signalling axis." (PMID 39581695, 2024). "This suggests that the Keap1-Nrf2 interaction has a critical role in the pathophysiology of depression." (PMID 30618863, 2018). "The purpose of this study was to examine the role of Keap1-Nrf2 signaling in the pathophysiology of depression using the potent Nrf2 activator, SFN and Nrf2 knock-out (KO) mice." (PMID 27470577, 2016). "The present data demonstrated a key role for the Keap1-Nrf2 system in the pathophysiology of depression." (PMID 27470577, 2016). "The transcription factor Keap1-Nrf2 system plays a key role in inflammation which is involved in depression." (PMID 27470577, 2016). "Another study suggests that major depressive disorder (MDD) patients’ parietal cortex showed lower levels of Nrf2 and Keap1 expression than the control group, suggesting that decreased Keap1–Nrf2 signaling could be a major factor in the onset of depression." (PMID 40149774, 2025). "Moreover, the use of a corticotropin-releasing hormone receptor 1 (CRHR1) antagonist has been shown to reduce oxidative stress by inhibiting the Keap1-Nrf2-p62 pathway, thereby alleviating depression-like behaviors in PSD by reducing abnormal p62 accumulation." (PMID 39655159, 2024). "Enhancing circSpna2 expression could mitigate depression after TBI by modulating the Keap1/Nrf2/Atp7b pathway." (PMID 39581695, 2024).